PRL (prolactin)
Diseases named in the same sentence as PRL in open-access papers (continued):
Sharing a sentence is not in itself a finding about the gene and the disease.
adenomyosis (continued). "A possible explanation for the formation of adenomyosis in these mice is the action of elevated prolactin levels to increase the ability of endometrial stromal cells to invade the myometrium through degradation of the extracellular matrix with matrix metalloproteinases." (PMID 39407928, 2024). "In the future, more human studies are required to elucidate the prolactin hypothesis in adenomyosis and investigate the effect of bromocriptine on healthy endometrial tissue as well." (PMID 36967761, 2023). "It has been proposed that increased levels of prolactin (PRL) may contribute to the development of adenomyosis." (PMID 36967761, 2023). "As far as we know, the current evidence for the prolactin hypothesis was promoted by murine models of adenomyosis." (PMID 36967761, 2023). "Several animal studies have shown that uterine PRL may contribute to the pathogenesis of adenomyosis." (PMID 36967761, 2023). "In endometrial cancer cells, autocrine PRL expression stimulates cell proliferation, migration and invasion, and promotes tumour growth, local invasion and metastases, processes that are important in adenomyosis pathogenesis." (PMID 35773139, 2022). "Taken together, these observations suggest that high levels of PRL or hyperprolactinism could lead to the development of adenomyosis." (PMID 35330066, 2022). "CCND1 is a key component of PRL signalling and may be a factor in endometrial cell proliferation and adenomyosis." (PMID 35773139, 2022). "Additionally, we monitored prolactin production after estradiol and progesterone treatments in adenomyosis, as a functional investigation of potentially activated pathways." (PMID 35956024, 2022). "Although PRL signaling has been implicated in uterine abnormalities, including adenomyosis,41–44, the direct causal role of exaggerated PRL signaling in the pathogenesis and development of adenomyosis has not been established." (PMID 40804233, 2025). "Subsequent studies suggested there may be evidence for the role of prolactin in human adenomyosis." (PMID 36967761, 2023). "Hence, considering the complex pathologies of adenomyosis, more well-designed human studies including healthy controls are needed to elucidate PRL expression patterns in endometrial tissue, as well as the role of dopamine in PRL regulation in endometrial tissue in humans." (PMID 36967761, 2023). "The expression of prolactin (PRL) and prolactin receptor (PRLR) was significantly upregulated in adenomyosis compared to normal myometrium." (PMID 35956024, 2022). "In pituitary-isograft mice, we found that localized PRL signaling, rather than systemic PRL elevation, strongly influences adenomyosis development." (PMID 40804233, 2025). "Immunohistochemical staining revealed increased expression of PRLR in the absence of increased serum PRL levels in adenomyosis patients." (PMID 40804233, 2025). "Prolactin (PRL) expression has increased in women with adenomyosis compared to those without adenomyosis." (PMID 39201621, 2024). "Vaginal bromocriptine treatment reduced the Ki67 protein expression in the endometrium of women with adenomyosis and did not change the prolactin mRNA expression and protein concentration of prolactin in endometrial tissues." (PMID 36967761, 2023). "More recently, higher serum levels of PRL in women with adenomyosis compared with those without disease have been reported." (PMID 35773139, 2022). "Uterine horns that underwent surgery without pituitary transplantation developed adenomyosis less frequently than those that received a transplant, highlighting that exacerbated local PRL signaling, rather than mechanical injury alone, triggers the development of the disease." (PMID 40804233, 2025). "In fact, we did not observe elevated serum PRL levels in adenomyosis patients." (PMID 40804233, 2025).
adenomyosis (continued). "Studies have found that progesterone can stimulate the endometrial secretion of prolactin (PRL), and the signaling pathway mediated by the significant upregulation of PRL and its receptor PRLR may enhance uterine peristalsis in adenomyosis, facilitating the establishment of lesions." (PMID 39595579, 2024). "Based on the current evidence from this study, we could conclude that the local endometrial PRL level does not correlate with the anti-proliferation effect of bromocriptine in adenomyosis." (PMID 36967761, 2023). "However, we did not observe a significant reduction in PRL level in the endometrium in women with adenomyosis after bromocriptine treatment." (PMID 36967761, 2023). "Furthermore, PRL has an effect on myometrial smooth muscle cells, but ovariectomized pituitary-grafted C57 mice neonatally fed with tamoxifen do not seem to develop adenomyosis; rather, they show a disordered arrangement of the myometrium." (PMID 35330066, 2022). "Also, our results underscore the importance of PRL signalling in the endometrium and myometrium of women with versus without adenomyosis, providing opportunity for developing targeted treatments for the disease." (PMID 35773139, 2022). "In the present study, the PRL signalling pathway was enriched in DEG of both endometrium and myometrium of women with versus without adenomyosis (enrichment scores of 1.955 and 2.23, respectively)." (PMID 35773139, 2022).
Autoimmunity (19 papers, 2013 to 2025). The occurrence of an immune reaction against the organism's own cells or tissues. "Thus, although there is a clear relationship between PRL, Th17 cells, and autoimmunity, the underlying mechanisms remain to be fully elucidated." (PMID 36389803, 2022). "Besides these effects, prolactin requires a genetic susceptibility background to produce autoimmunity." (PMID 25431724, 2014). "Furthermore, prolactin is associated with inflammatory, anti-inflammatory effects and autoimmunity." (PMID 36389068, 2022). "Therapeutically, bromocriptine—a dopamine agonist that reduces PRL levels—has shown promise in managing these autoimmune conditions." (PMID 41476991, 2025). "Our work not only provides clinical validation for PRL-driven autoimmunity in GLM but also highlights its potential as a therapeutic target for rebalancing immune tolerance." (PMID 40948778, 2025). "There are some reports showing that PRL promotes autoimmunity via modulating the activation of lymphocytes and pDCs." (PMID 36389803, 2022). "This indicates that PRL participation is a step between the trigger (antigen presentation) and costimulatory signal, which is a relevant step in the development of autoimmunity, particularly in SLE." (PMID 36389803, 2022). "Prolactin is immune stimulator and promotes autoimmunity by increasing IL-2, IFN-gamma, and autoantibody by regulating Th1 and Th2 lymphocytes, respectively." (PMID 34746311, 2021). "Prolactin, the levels of which are elevated in the postpartum period, has immunostimulatory effects and can promote autoimmunity." (PMID 27642532, 2016). "Thus, the data presented in this review clearly show the relevance of PRL in autoimmunity, particularly due to its role as a modulator of both innate and adaptive immune responses." (PMID 36389803, 2022). "The gender dimorphism of SLE is usually attributed to the fact that alterations in the immune-neuroendocrine system contribute to the development of autoimmunity, and therefore it is suggested that hormones, such as prolactin (PRL), modulate the immune response influencing the development of SLE." (PMID 36389691, 2022). "This may indicate a response meant to counter another, harmful effect of prolactin: inflammation that leads to autoimmunity." (PMID 34768809, 2021). "It has been shown that autoimmune disorders were accompanied by increased PRL levels." (PMID 32597541, 2020). "Concentration-dependent effects of estrogen on the immune system; the role of progesterone, androgens, leptin, oxytocin, and prolactin; and the interplay between Th1 and Th2 immune responses together maintain a delicate balance between host defense, immunological tolerance and autoimmunity." (PMID 31110493, 2019). "The link between PRL and autoimmunity has been proposed to have a genetic background." (PMID 29483903, 2018). "It has been proposed that, in Th2-mediated autoimmune processes, prolactin may be involved in the progression of Th2-mediated autoimmunity through its direct effects on Th2-related antibody production." (PMID 27642532, 2016). "Except for autoimmunity, thyroid dysfunction may influence the reproductive system via thyroid hormone receptors on the surface of oocytes, or through disruption of GnRH function due to increasing prolactin secretion." (PMID 31064360, 2019). "It will be interesting to determine the molecular mechanisms by which PRL and PRL receptors interfere with B cell maturation and tolerance, which will aid in the rational design of targeted therapy with potential applications for both autoimmunity and immunodeficiencies." (PMID 24454471, 2013). "Thyroid function and autoimmunity, sonographically measured thyroid volume, FSH and E2 in the early follicular phase, and PRL and progesterone in the luteal phase were also evaluated." (PMID 35965323, 2022). "Prolactin (PRL) has a recognized immune-stimulatory effect, specially inhibiting the negative selection of autoreactive B lymphocytes, promoting autoimmunity." (PMID 29483903, 2018).
Autoimmunity (continued). "Prolactin has been shown to play significant roles in antigen presenting functions and in the initiation of the response against major histocompatibility complex (MHC) presenting self-antigens as found in autoimmunity." (PMID 24804084, 2014). "Interestingly, prolactin concentrations at slightly higher levels than the physiological range but not those vastly superior induce an increased production of IgG by mononuclear cells from SLE patients, thus creating a prolactin threshold for its contribution to autoimmunity." (PMID 25431724, 2014).
preeclampsia (19 papers, 2013 to 2025). Preeclampsia is a hypertensive disorder of pregnancy that is characterized by new-onset hypertension with proteinuria presenting after 20 weeks of gestation, and depending on mild or severe forms may initially present with severe headache, visual disturbances, and hyperreflexia. "Increased prolactin levels were positively associated with disease severity and estradiol and progesterone levels were decreased in poorer preeclampsia features including disease onset and IUGR diagnosis." (PMID 35885604, 2022). "Altered decidualization, measured by reduced expression of decidual markers such as prolactin (PRL), has been linked to pregnancy complications, including miscarriage, preeclampsia, and intrauterine growth restriction." (PMID 40943115, 2025). "These resulted in higher levels of vasoinhibins in patients with preeclampsia, including 16-kDa PRL." (PMID 38254703, 2024). "Studies have demonstrated an increase in antiangiogenic PRL fragments in amniotic fluid and urine of women with preeclampsia and in diabetic placentas, a significant increase in PRL gene expression was observed." (PMID 39763651, 2024). "A strong signature of dysregulated decidual gene expression (e.g., decreased levels of IGFBP1, glycodelin, PRL and IL-15) also emerged among women with severe preeclampsia compared with those experienced normal pregnancies." (PMID 37404833, 2023). "The levels of PRL in the urine were significantly higher in patients with preeclampsia than in subjects with normal pregnancy and antiangiogenic PRL fragments (14-16 kDa) in urine was detected only in patients with severe preeclampsia." (PMID 36704037, 2022). "A dysregulation of vasoinhibin generation during preeclampsia is indicated by higher vasoinhibin, prolactin, placental lactogen, and vasoinhibin-generating enzymes levels and activity." (PMID 31998232, 2019). "The mean cord blood prolactin of neonates was 288.04± 92.46 ng/ml, and it also showed highly significant differences between the groups being higher in neonates of gestational hypertension group (P= 0.000) (Table-I)." (PMID 31372154, 2019). "The average maternal prolactin was 255.90± 88.56 ng/ml and it was significantly different between the groups being higher in women with gestational hypertension (P= 0.011) as seen in Table-I." (PMID 31372154, 2019). "Regarding maternal prolactin, the only significant difference was seen between preterm labour and gestational hypertension groups (P= 0.009)." (PMID 31372154, 2019). "Selected original research articles and reviews supporting the involvement of the prolactin/vasoinhibin axis in preeclampsia." (PMID 31998232, 2019). "Dysregulation of the PRL/vasoinhibin axis has been brought into context with diabetic retinopathy, retinopathy of prematurity, preeclampsia, and pregnancy-induced hypertension." (PMID 29163363, 2017). "Another study showed that prolactin fragments with antiangiogenic effects are highly expressed in the placentas of gestational hypertension, whereas the expression of Cat D in the placentas of the gestational hypertension group is significantly decreased." (PMID 37794357, 2023). "Whether aspirin therapy for the prevention of preeclampsia or bromocriptine to block prolactin impacts the incidence of or recovery from PPCM is unknown." (PMID 36005414, 2022). "Also, by comparing cord blood prolactin between normal uncomplicated pregnancy and pregnancy with gestational hypertension, it was found that cord blood prolactin is significantly higher in neonates born to hypertensive mothers." (PMID 31372154, 2019). "Also, cord prolactin in gestational hypertension group was significantly higher than diabetic (P=0.006) and preterm labour (P=0.000) groups." (PMID 31372154, 2019). "Additionally, this list included several genes associated with preeclampsia (PE) such as TIMP3, Wnt regulator DKK1, fibronectin FN1, cannabinoid receptor CNR1, neurokinin receptor TAC3, retinol binding protein RBP4, and prolactin PRL." (PMID 30131724, 2018).
preeclampsia (continued). "Recent experimental and clinical studies reported that pregnancy-induced hypertensive conditions such as preeclampsia may be a risk factor for PPCM by providing an extremely anti-angiogenic environment which may include sFlt1 and 16 kDa Prolactin." (PMID 23812247, 2013). "In the present study, we report the immunometric measurement of endogenous vasoinhibin in the serum of pregnant women without and with preeclampsia using a novel enzyme-linked immunosorbent assay (ELISA) with an anti-vasoinhibin monoclonal antibody (vi-mab), which shows no cross-reactivity with PRL." (PMID 38742198, 2024).
chronic kidney disease (18 papers, 2009 to 2025). Impairment of the renal function secondary to chronic kidney damage persisting for three or more months. "The main results of our study indicate that inflammatory syndrome biomarker IL-1 beta, muscular mass, and NT proBNP were the most significant factors associated with prolactin levels in chronic kidney disease." (PMID 40650124, 2025). "In conclusion, our study demonstrated that prolactin in patients with chronic kidney disease is a hormone associated with numerous metabolic pathways." (PMID 40650124, 2025). "It has been shown that pathological PRL level is linked with cardiovascular complications due to alteration of lipid metabolism and development of endothelial dysfunction in patients with chronic kidney disease." (PMID 39663784, 2024). "Specifically, the deletion/deletion carriers of rs3840963 of Adrenomedullin 2 (ADM2), encoding proteins that regulate cardiovascular homeostasis and prolactin release, suffered from higher risk of chronic kidney disease, CI and WMH." (PMID 33352859, 2020). "Therefore, this study aims to evaluate the factors associated with prolactin levels in individuals with chronic kidney disease at various stages in our region." (PMID 40650124, 2025). "In chronic kidney disease, serum prolactin levels increase as the estimated glomerular filtration rate (eGFR) decreases." (PMID 40650124, 2025). "The increase in prolactin levels was correlated with a decrease in estimated glomerular filtration rate, suggesting that prolactin levels rise as chronic kidney disease progresses." (PMID 40650124, 2025). "PRL has a short half‐life; it is metabolized by liver and excreted by kidney, thus PRL serum level is augmented in chronic renal failure." (PMID 39663784, 2024). "Elevated prolactin levels in chronic kidney disease (CKD) primarily result from reduced clearance and heightened secretion." (PMID 39200324, 2024). "PRL levels can be even higher in the patient with chronic kidney disease consuming medications that interfere with dopaminergic inhibition of PRL." (PMID 35000899, 2022). "In chronic renal disease, decreased renal clearance and imbalance of neurotransmitters increase serum PRL in the range of 30–100 ng/mL." (PMID 35000899, 2022). "Nearly 30% of patients with chronic kidney disease have high serum prolactin levels probably secondary to impaired renal excretion of prolactin." (PMID 25518745, 2014). "However, further clarification is needed regarding the role and place of prolactin in cardiovascular disease in chronic kidney disease." (PMID 40650124, 2025). "In addition, patients with chronic kidney disease can experience elevated prolactin levels because of reduced prolactin clearance and changes in central prolactin regulation." (PMID 38338751, 2024). "Patients’ prolactin levels were reported for five cases; they were low in four cases and elevated in one case, in which the patient had severe peripartum hemorrhage leading to chronic kidney disease." (PMID 34779875, 2022). "Furthermore, lifestyle, in conjunction with regional dietary habits and microbiota characteristics, may influence prolactin levels and their interactions in chronic kidney disease across different population groups." (PMID 40650124, 2025). "Thus, dopaminergic inhibition of prolactin secretion might be reduced in patients with end-stage renal disease." (PMID 28791188, 2017). "In pre-dialysis chronic kidney disease (CKD) patients, a direct correlation between prolactin and fat mass was observed in men in another study." (PMID 40650124, 2025). "Both the clearance and secretion of prolactin are disrupted in chronic kidney disease (CKD)." (PMID 40021736, 2025). "Our study’s age-related variation in prolactin was similar to that reported in some studies of patients without chronic kidney disease." (PMID 40650124, 2025).
chronic kidney disease (continued). "In patients without chronic kidney disease, elevated prolactin levels lead to changes in the lipid profile, increasing LDL-cholesterol and triglycerides while decreasing HDL." (PMID 40650124, 2025). "Sexual hormones (e.g., estradiol, testosterone, prolactin and FSH) concentrations are commonly affected by chronic renal failure and the dysfunction of sex steroids may contribute to the emergence of renal osteodystrophy." (PMID 19781091, 2009). "A recent study found that prolactin levels may not substantially influence the relationship between chronic kidney disease and cardiovascular disease." (PMID 40650124, 2025).